PRX (periaxin)
Description:
Scaffolding protein that functions as part of a dystroglycan complex in Schwann cells, and as part of EZR and AHNAK-containing complexes in eye lens fiber cells. Required for the maintenance of the peripheral myelin sheath that is essential for normal transmission of nerve impulses and normal perception of sensory stimuli. Required for normal transport of MBP mRNA from the perinuclear to the paranodal regions. Required for normal remyelination after nerve injury. Required for normal elongation of Schwann cells and normal length of the internodes between the nodes of Ranvier. The demyelinated nodes of Ranvier permit saltatory transmission of nerve impulses; shorter internodes cause slower transmission of nerve impulses. Required for the formation of appositions between the abaxonal surface of the myelin sheath and the Schwann cell plasma membrane; the Schwann cell cytoplasm is restricted to regions between these appositions. Required for the formation of Cajal bands and of Schmidt-Lanterman incisures that correspond to short, cytoplasm-filled regions on myelinated nerves. Recruits DRP2 to the Schwann cell plasma membrane. Required for normal protein composition of the eye lens fiber cell plasma membrane and normal eye lens fiber cell morphology.
Synonyms: KIAA1620; CMT4F
Tractability: Antibody: its Gene Ontology location is reachable by antibodies, with high confidence; UniProt places it where antibodies can reach, with medium confidence; the Human Protein Atlas places it where antibodies can reach.
Gene: Protein-coding gene on chromosome 19 (40,393,764 to 40,415,070, reverse strand). Ensembl gene ENSG00000105227.
Subcellular location: Cell membrane (Isoform 1); Nucleus; Cytoplasm; Cytoplasm (Isoform 2); Cell membrane; Cell junction
Subcellular location (Human Protein Atlas): Golgi apparatus; Plasma membrane; Vesicles
Pathways (Reactome):
Developmental Biology: EGR2 and SOX10-mediated initiation of Schwann cell myelination
Gene Ontology:
Molecular function: protein binding
Biological process: axon ensheathment; peripheral nervous system myelin maintenance; regulation of RNA splicing
Cellular component: cytoplasm; nucleus; plasma membrane; anchoring junction
Genetic constraint (gnomAD): Loss-of-function variants: 29 observed, 29.93 expected, observed/expected ratio (o/e) 0.97, 90% interval 0.72 to 1.32. The upper end of that interval is the gene's LOEUF score, 1.32, which puts it in group 5 of 6, group 1 being the genes least tolerant of losing a copy. Missense variants: 1,836 observed, 1,906.6 expected, observed/expected ratio (o/e) 0.96, 90% interval 0.93 to 1. Synonymous variants: 772 observed, 811.55 expected, observed/expected ratio (o/e) 0.95, 90% interval 0.9 to 1.01.
Gene-disease validity (ClinGen):
ClinGen rates the evidence that PRX causes each of these diseases.
Charcot-Marie-Tooth disease type 4 (autosomal recessive): Definitive. Charcot-Marie-Tooth disease type 4 (CMT4) belongs to the genetically heterogeneous group of CMT peripheral sensorimotor polyneuropathy diseases.
Homologues: Orthologues: macaque PRX (93% identical), dog PRX (84% identical), chimpanzee PRX (82% identical), pig PRX (81% identical), rat Prx (75% identical), rabbit PRX (73% identical), mouse Prx (68% identical), tropical clawed frog prx (27% identical). Paralogues in human: AHNAK2 (22% identical), AHNAK (21% identical).